CCL2 (C-C motif chemokine ligand 2)
Diseases named in the same sentence as CCL2 in open-access papers (continued):
Sharing a sentence is not in itself a finding about the gene and the disease.
epilepsy (41 papers, 2009 to 2025). A brain disorder characterized by episodes of abnormally increased neuronal discharge resulting in transient episodes of sensory or motor neurological dysfunction, or psychic dysfunction. "CCL2 signaling is extensively intertwined with epilepsy, simultaneously serving as a cause and consequence of both neuronal hyperexcitability and injury." (PMID 31058213, 2019). "To this end, we analyzed the transcript levels of the inflammasome mediators Il1β, Il6, Il12, Il10, Tnfα, Cd68, Ccl2, and Ccl5, which are upregulated in pilocarpine‐ and kainic acid‐induced epilepsy models." (PMID 40608247, 2025). "Genes differentially expressed in human TLE samples and previously implicated in epilepsy (XIRP1, CCL2, and NPAS4), were predicted to have potential methylation sites and showed inverse expression changes to those found for snoRNAs in human TLE." (PMID 39509000, 2024). "The scRNA‐seq of non‐affected brain areas of patients with epilepsy revealed 10 distinct microglial clusters, with the genes CCL2, CCL4, and SPP1 being involved." (PMID 38572804, 2024). "CCL2 can be produced by neurons, microglia, astrocytes, and endothelial cells within the CNS, and CCL2 expression is highly induced in the brains of patients with epilepsy as well as in the brains of animal models of epilepsy." (PMID 38257819, 2024). "For example, in a mouse model of kainic acid- (KA-) induced epilepsy, it was found that CCL2 expression in the hippocampus increased significantly after 24 hours of lateral ventricular injection of KA." (PMID 32185196, 2020). "On the other hand, similarly as after SE, ECS resulted in increased gene and protein expression of Ccl2/CCL2, a chemokine with an established role in neuron-glia-inflammation crosstalk in healthy states and in seizures/epilepsy." (PMID 31058213, 2019). "However, studies in children with epilepsy have shown a significant decrease in C–C Motif Ligand 2 (CCL2)." (PMID 40872604, 2025). "The antiepileptic drugs, namely, valproate and levetiracetam can lead to a decrease in serum CCL2 levels in children with epilepsy, suggesting that CCL2 may be a potential target for epilepsy drug therapy." (PMID 40103702, 2025). "Increased levels of CCL2 are described in the resected tissue of epilepsy patients." (PMID 35625063, 2022). "The literature suggests that chemokines, particularly CCL2, may well play a role in the pathogenesis of epilepsy." (PMID 35625063, 2022). "Moreover, the expression of other pro‐inflammatory genes associated with epilepsy, such as IL1B and CCL2, was decreased by miR‐132 overexpression in astrocytes." (PMID 31408236, 2020). "The expression of CCL2 has been reported in several forms of epilepsy, and the levels of CCL2 in blood or cerebrospinal fluid (CSF) may be used as biomarkers of the progression of the disease." (PMID 32521797, 2020). "We showed that CBD significantly reduces the transcript levels of the proinflammatory immune biomarkers IL‐12, CD68, CCL2, and IRF3, found previously upregulated in rodent models of induced epilepsy and in pediatric patients with encephalopathy." (PMID 40608247, 2025). "Furthermore, research involving children with epilepsy demonstrated that treatment with valproate led to a significant decrease in serum levels of C–C motif ligand 2 (CCL2), a chemokine associated with inflammation, without altering levels of interleukin-1 beta (IL-1β)." (PMID 40507116, 2025). "Serum levels of MMP-9, MMP-2, TIMP-1, TIMP-2, S100B, CCL-2, ICAM-1, P-selectin, and TSP-2 were examined in a group of 49 patients with epilepsy who were seizure-free for a minimum of seven days and measured by ELISA." (PMID 36499038, 2022). "We measured the serum interictal quantitative levels of chemokines (CCL2, CCL4, CCL11) and PGE2 in correlation with the seizure frequency and severity in controlled and intractable childhood epilepsies." (PMID 36291442, 2022).
epilepsy (continued). "CCL2 exhibits binding affinity toward the G protein‐coupled receptor known as C‐C Chemokine receptor 2 (CCR2), which has been observed to be notably upregulated in individuals diagnosed with drug‐resistant epilepsy." (PMID 40103702, 2025). "A set of molecules associated with BBB permeability (MMP-2, MMP-9, S100B), restoration (TIMP-1, TIMP-2, TSP-2), neuroinflammation (CCL-2), and endothelial activation (ICAM-1, P-sel) that are affected in epilepsy and can be measured in blood was selected in this study." (PMID 36766708, 2023). "In pharmacoresistant epilepsy, CCR2 is highly expressed in neurons and monocytes suggesting that CCL2 and its receptor may play a role in epileptogenesis." (PMID 34512245, 2021). "In the context of epilepsy, CCL2 expression is robustly upregulated in human epileptic brain tissue, leading to the hypothesis that CCL2/CCR2 signaling may play a role in the pathogenesis and progression of epilepsy." (PMID 31717556, 2019).
Granuloma (41 papers, 2005 to 2025). A compact, organized collection of mature mononuclear phagocytes, which may be but is not necessarily accompanied by accessory features such as necrosis. "CCL2 is a strong chemoattractant for monocytes and macrophages and implicated in granuloma development, a known sequela of CD inflammation." (PMID 29867993, 2018). "Collectively, these results demonstrate in vivo that ablation of the variable macrophage immune receptor in murine lung tuberculosis is associated with suppression of CCL2 and defective granulomas formation." (PMID 22114556, 2011). "Elevation of CCL2 in BAL cells was unexpected in Mmp12 KO mice at 60 days after MWCNT instillation when granulomas had resolved." (PMID 33072094, 2020). "Bronchoalveolar lavage (BAL) cells, BAL fluids, and lung tissues were obtained 60 days post-instillation for analysis of granuloma histology and pro-inflammatory cytokines (osteopontin, CCL2, and interferon gamma [IFN-γ] mRNA and protein expression." (PMID 23343389, 2013). "Although CCL2 seems to have a relatively low expression in in vivo models of disease, it has been demonstrated to play an important role in early granuloma regulation." (PMID 23840855, 2013). "This cascade culminates in the expression of many NF-κB-inducible genes, including CCL2, IL1B, IL12, IL18 and TNF, causing natural killer (NK) and T cells to release IFN-γ and TNF-α, which ultimately results in granuloma formation." (PMID 22182502, 2011). "CCL2 expression is important for the development of granulomas and fibrosis in schistosomiasis mansoni." (PMID 20161726, 2010). "In agreement, we see upregulation of Ccl2 in several clusters and deposition of CCL2 protein in wide areas around granulomas, further suggesting that CCL2 may be a critical chemokine that promotes monocyte recruitment in response to C. violaceum." (PMID 38352492, 2024). "Interestingly, a role of MMP12 in granuloma resolution is also suggested by increases in both macrophage influx and CCL2." (PMID 33072094, 2020). "Oropharyngeal aspiration of thermally purified MWCNTs or its carboxyl- or amine-functionalized derivatives was associated with greater lung toxicity, increased OPN and CCL2 in BALF, and greater numbers granulomas compared to functionalized derivatives of chemically purified MWCNTs." (PMID 33243293, 2020). "Whether glucocorticoids help in the prevention of granuloma development by decreasing CCL2 levels remains unknown." (PMID 29867993, 2018). "It has been postulated that the presence of Monocyte Chemoattractant protein-1 (MCP-1/CCL2) may be responsible for the innate pulmonary inflammatory response and the development of granuloma." (PMID 29456774, 2018). "Moreover, ccl2-/- mice were found to develop smaller granulomas in this model of egg induced granuloma formation." (PMID 25144366, 2014). "Fibroblasts isolated from schistosome granuloma tissue have been demonstrated to express CCL2." (PMID 23840855, 2013). "japonicum eggs induced a significant increase in the gene expression of the proinflammatory mediators MMP9, CCL2 (chemokine (C-C motif) ligand 2) and IL-6 (Interleukin 6), suggesting a potential role in the regulation of granuloma development via inflammatory cell recruitment and matrix remodelling." (PMID 23840855, 2013). "The production of CCL2, CXCL9, and CXCL8 modifies the type of tuberculous disease that a patient has, and they play a special role in the formation of granuloma." (PMID 32377537, 2020). "In rats, MCP1 (also known as CCL2) and its receptor, CCR2, are essential for the recruitment of DCs, formation of granulomas, antigen presentation, and T-cell responses." (PMID 29670625, 2018). "In contrast with these results, we did not observe a significant decrease in M1 marker genes, including MMP9, NOS2, CCL2, IL-6 and ARG2, in granuloma FCMs compared with NFMs, although MMP13 and NF-κB1 levels, which are also M1-related genes, were decreased." (PMID 26197235, 2015).
Granuloma (continued). "There was a strong correlation between mRNA induction of CCL2 and MIP-2 and the number of granulomas (r = 0.84, and r = 0.67, respectively; p<0.0001)." (PMID 22457760, 2012). "Overall this study suggests that CCL2 and CCL5 may be interacting with mononuclear cells expressing specific CC chemokines receptors (CCL2 → CCR2, CCL5 → CCR1, CCR3, and CCR5) and are important biologically in the formation of pulmonary sarcoidosis granulomas." (PMID 21463523, 2011). "We found that the main cellular source of CCL2 was epithelioid histiocytes, multinucleated giant cells, surrounding alveolar macrophages with a minor component being other infiltrating mononuclear cells that formed the non-necrotizing granulomas." (PMID 21463523, 2011).
myeloma (41 papers, 2003 to 2025). "We previously showed that the chemokine CCL2 can recruit macrophages (Mφs) to the bone marrow (BM) in multiple myeloma (MM) and that myeloma-associated Mφs are important in drug resistance." (PMID 31611552, 2019). "CCL2 stimulated proliferation and polarization of human macrophages (generated with M-CSF) into myeloma-associated macrophages, a subset of bone marrow infiltrating cells in multiple myeloma that has been shown to be responsible for drug resistance." (PMID 31921102, 2019). "Moreover, CCL2 induced expression of myeloma-associated macrophage markers IL-6 and c-myc when added to the media, compared to CCL2-untreated cells." (PMID 31921102, 2019). "MSCs associated with multiple myeloma exhibit diminished osteogenic differentiation, elevated secretion of IL-6 and CCL2, and increased facilitation of myeloma cell proliferation and drug resistance." (PMID 40140850, 2025). "Other BMAT-derived factors, such as MCP-1/CCL2 and stromal cell-derived factor-1α, function as chemotactic agents for multiple myeloma cells." (PMID 40852589, 2025). "In multiple myeloma (MM), MSCs from patients show altered osteogenic differentiation potential, increased secretion of pro-inflammatory cytokines such as IL-6 and CCL2, and enhanced support for tumor growth." (PMID 40140850, 2025). "In multiple myeloma, mesenchymal stem cells facilitate immune evasion through the secretion of cytokines, including IL-6 and CCL2, which enhance the survival and proliferation of multiple myeloma cells while suppressing immune cell activity." (PMID 40140850, 2025). "Those myeloma-associated macrophages are an essential factor in drug resistance by interacting with myeloma cells and upregulating their CCL2 expression." (PMID 33540898, 2021). "TNF-α independently promoted the proliferation of myeloma cells, and induced the expression of CCL2 in myeloma cells together with IL-6." (PMID 31334678, 2019). "CCL2 leads to the macrophage recruitment that supports myeloma cell survival, drug resistance, and angiogenesis." (PMID 31334678, 2019). "In turn, CCL2 upregulates the expression of MCP-1-induced protein (MCPIP1) in macrophages which triggers their polarization into the M2 phenotype that protects the myeloma cells from drug-induced apoptosis." (PMID 33540898, 2021). "In multiple myeloma, CCL2 can recruit macrophages to the bone marrow." (PMID 33540898, 2021). "Adipocyte-derived factors such as MCP-1/CCL2 and SDF1α/CXCL12 are chemotactic factors for myeloma cells, while other adipokines promote myeloma proliferation (e.g., leptin/LEP) and resistance to chemotherapies (e.g., leptin/LEP, adipsin/CFD)." (PMID 33680918, 2020). "The significance of CCL2/CCR2 signaling in osteoclast function is mirrored by its contribution to diseases of the bone, such as RA, osteoporosis, multiple myeloma, tooth eruption, and bone metastasis." (PMID 31921102, 2019). "We found that chemokines CCL3, CCL14, and CCL2 were highly expressed by myeloma and BM cells, and the levels of CCL14 and CCL3 in myeloma BM positively correlated with the percentage of BM-infiltrating MΦs." (PMID 26155942, 2015). "Other nodules in the network correspond to cytokines with known function in myeloma pathophysiology and/or in osteolytic lesions (IL6, IL1β, CCL2, IL8 and CCL20)." (PMID 25268740, 2014). "We found that distinct to full length CCL2 or its N-truncated derivative (CCL2 5-76), GMME1 bound to CCR2 on mouse lymphoma EG7, human multiple myeloma cell line U266, or murine and human medulloblastoma cell lines, and led to their death by apoptosis." (PMID 21943176, 2011). "In vivo multiple myeloma mouse model, bone marrow stromal cell (BMSC)-derived exosomes contain oncoproteins, cytokines, adhesion molecules, such as IL-6, CCL2, and fibronectin, which can induce the survival, proliferation, and migration of multiple myeloma cells." (PMID 35692747, 2022).
neuroblastoma (40 papers, 2009 to 2026). Neuroblastoma (NB) is the most common solid, extracranial childhood tumor. "Upon analysis of gene expression profiles of neuroblastoma tumor samples, we found that increased CCL2 gene expression was associated with advanced disease, disease progression, and increased mortality." (PMID 37964011, 2023). "iNKT cell infiltration is associated with CCL2 expression in neuroblastoma cells and CCL20-producing tumor-associated macrophages." (PMID 36830717, 2023). "In agreement with our in vitro data, we observed an increased representation of DC-associated genes in neuroblastoma with higher CCL2 expression, further illustrating the role of CCL2 in the active recruitment of DCs." (PMID 36923280, 2022). "Our data suggest that monocytes and DC recruitment is directly associated with CCL2 secretion by neuroblastoma cells, as already shown for iNKT." (PMID 36923280, 2022). "Dual-luciferase reporter assays were conducted in neuroblastoma cells to assess the promoter transcriptional activity of the rs1024611 variants (T>C) and the GRCh38.p12chr17:34252593 G>C alleles in CCL2." (PMID 30761072, 2019). "Expression of chemokine CCL2 has long been associated with more effective immune responses against neuroblastoma and it is secreted by neuroblastoma cell lines and primary tumor cells." (PMID 30459759, 2018). "These cells migrate toward neuroblastoma tumor cells in a CCL2-dependent manner, and CCL2 expression is inversely associated with MCYN amplification." (PMID 26729169, 2015). "Future study of CCL2 targeting in immunocompetent models of neuroblastoma may aid in elucidating the effect of CCL2 inhibition on tumor-associated macrophage proliferation and metastatic tumor burden." (PMID 37964011, 2023). "However, as MYCN amplification accounts for only 50% of all high-risk neuroblastoma cases, CCL2 may be a potential factor associated with increased risk in tumors that are not MYCN-amplified." (PMID 37964011, 2023). "A new research team found that resiquimod enhances immunological response in human neuroblastoma cell cultures via TLR7-NFκB-C-C motif chemokine ligand 2 signaling, providing a novel possible therapy approach for neurotropism due to viruses." (PMID 40673003, 2025). "In particular, proNT3 knockdown blocked the paclitaxel-induced CCL2 expression in in vitro human neuroblastoma cell lines." (PMID 41299083, 2025). "High expression levels of CCL2, CCL4, CCL21, CD200, CXCR3, and IGSF6 were significantly associated with improved survival in neuroblastoma patients (all p < 0.001)." (PMID 40718780, 2025). "In vitro, the CCL2 concentration-dependent migration of neuroblastoma cells and monocytes was observed, which was abrogated with the addition of carlumab." (PMID 37964011, 2023). "With regards to the expression of CCL2 itself, when neuroblastoma cells and monocytes were co-cultured, the expression of CCL2 was markedly higher than the expression of CCL2 from either cell population alone." (PMID 37964011, 2023). "In vitro and in vivo studies have demonstrated that CCL2-attracted TAMs in neuroblastoma enhance IL-6 expression, promote tumor growth and inhibit apoptosis." (PMID 38087370, 2023). "Two-dimensional time-lapse microscopy was performed to measure neuroblastoma cell movement across varying concentration gradients of CCL2 protein." (PMID 37964011, 2023). "The effect of anti-CCL2 antibody on neuroblastoma cells was determined in vitro with cell proliferation, transwell migration, and 2-dimensional chemotaxis migration assays." (PMID 37964011, 2023). "Through subsequent studies, the primary source of CCL2 expression was from monocytes, but neuroblastoma cells, interestingly, also produce CCL2." (PMID 37964011, 2023). "In vivo, CCL2 inhibition combined with etoposide leads to increased survival in a surgical resection mouse model of minimal residual disease of neuroblastoma." (PMID 37964011, 2023).